MTND4P12 (MT-ND4 pseudogene 12)
Gene: Processed pseudogene on chromosome 5 (134,926,660 to 134,928,036, reverse strand). Ensembl gene ENSG00000247627.
Diseases named in the same sentence as MTND4P12 in open-access papers:
MTND4P12 is named in the same sentence as 3 diseases in open-access papers, as found by Europe PMC text mining. Sharing a sentence is not in itself a finding about the gene and the disease. The quoted sentences say what the papers report.
cutaneous melanoma (2 papers, 2023 to 2025). A primary melanoma arising from atypical melanocytes in the skin. "MTND4P12 is considered as an oncogenic pseudogene upregulated in skin cutaneous melanoma, and it can upregulate the expression of oncogene AURKB by serving as ceRNA34." (PMID 37258695, 2023). "Hsa-let-7e-5p is also identified as candidate miRNA that regulated by MTND4P12, hsa-let-7e-5p and MTND4P12 is co-expression in skin cutaneous melanoma." (PMID 37258695, 2023). "Interestingly, MTND4P12 expression is negatively correlated with overall survival in cutaneous melanoma patients." (PMID 40781241, 2025).
calcification (1 paper, 2025). Process by which organic tissue becomes hardened by the physiologic deposit of calcium salts. "By contrast, the mitochondrial-related genes MTND5P11 (log2FC −4.788), MTND4P12 (log2FC −3.897) and MTND4LP30 (log2FC −3.774) were downregulated in individuals with coronary calcifications." (PMID 40703140, 2025).
MTND4P12 also shares sentences with these, for which no sentence is quoted: Obesity (1 paper).